IL2 (interleukin 2)
Diseases named in the same sentence as IL2 in open-access papers (continued):
Sharing a sentence is not in itself a finding about the gene and the disease.
COVID-19 (continued). "We further compared the cellular response in COVID-19 recovered patients with previous SARS-CoV-2 infection and our results indicate a significant increase in IFN-ɣ and IL-2 production after the first vaccine dose (d10), which is maintained longitudinally." (PMID 35401504, 2022). "In particular, COVID-19 moderate patients and recovered individuals from severe disease, when compared to HD, reported higher percentages of IFN-γ+IL-2+TNF+, IFN-γ+TNF+ and IL-2+TNF+ within CD4+ T cells." (PMID 35887351, 2022). "Representative dot-plots exemplify the contrast of CD3+CD8+ T cells simultaneously expressing IL-2, IFN-gamma, and PD-1 in whole blood samples exposed to polyclonal molecules from participants who experienced mild or severe COVID-19 throughout the follow-up." (PMID 35860236, 2022). "In COVID-19 patients, excessive release of cytokine, including IL1-β, IL-2, IL-6, IL-7, IL-8, IP10, MCP1, MIP1A, and tumor necrosis factor-α (TNF-α), exacerbated COVID-19 manifestation." (PMID 36203683, 2022). "In male participants, EGF, GM-CSF, IL-1ra, IL-1α, IL-1β, IL-2, IL-4, IL-7, IL-15, EOTAXIN, MDC, MIP-1α, MIP-1β, IFNα2, and sCD40L were significantly lower in COVID-19 patients compared to controls." (PMID 36554094, 2022). "In this study concentrations of TNF-α, IL-1b, IL-2, IL-4, IL-5, IL-6, IL-8, IL-10, IL-12 p70, GM-CSF, and IFN-γ were determined by a magnetic bead assay in tear film collected from 232 symptomatic COVID-19 patients." (PMID 35508669, 2022). "According to the immunological mechanisms, both viral vector and mRNA COVID-19 vaccines induced a strong activation of CD8+ and CD4+ T cells, as well as the production of IFNγ and IL-2." (PMID 36177033, 2022). "Serum levels of EGF, G-CSF, GM-CSF, IL-1ra, IL-1α, IL-1β, IL-2, IL-4, IL-7, IL-8, EOTAXIN, fractalkine, GRO, P-10, MDC, MIP-1α, MIP-1β, IFNα2, and sCD40L were significantly lower in female COVID-19 patients compared to controls." (PMID 36554094, 2022). "MMP-7, TGF-β, CCL2, CCL-3, CXCL-10, G-CSF, IFN gamma, IL-10, IL-2, IL-4, IL-6, IL-7, TNF-α, IL-6, and IGF-1 were studied for their correlation with mortality in all 40 COVID-19 patients." (PMID 36286038, 2022). "Future studies expanded these findings, demonstrating sustained increases in serum IL-2, IL-6, IL-10, and IFN-γ in severe COVID-19 cases, with higher IL-6 levels correlating with mortality risk." (PMID 35401519, 2022). "HD COVID-19 recovered HD patients also displayed a significant correlation between the humoral (IgG) and the cellular (IFN-ɣ and IL2) immune responses." (PMID 35401504, 2022). "The studies indicate that the levels of IL-2, IL-6, IL-7, IL-10, and TNF-α are elevated in COVID-19; moreover, the increased IL-6 levels were found to be associated with disease progression and severe cases." (PMID 35656183, 2022). "TGF-β and IL2 STAT5 signaling, as well as Complement system activation pathways were also upregulated in the Class-switched memory B cells during active COVID-19." (PMID 36532041, 2022). "COVID-19 patients show higher concentrations of IL-2, IL-7, IL-10, G-CSF, IP10 (CXCL10), MCP-1 (CCL2), MIP1a (CCL3) and TNF-α than non-COVID-19 patients." (PMID 35901034, 2022). "NKG2A expression is upregulated on NK cells and CTLs in COVID-19 patients, with a decreased capacity to produce CD107a, IFN-γ, IL-2, granzyme B and TNF-α., which suggests functional exhaustion of cytotoxic lymphocytes in COVID-19 patients." (PMID 35833134, 2022). "Severe COVID-19 patients admitted to intensive care unit showed higher level of pro-inflammatory cytokine including MCP1, MIP1α, IL2, IL7 and TNFα." (PMID 36369012, 2022). "Elevated inflammatory biomarkers like C-reactive protein (CRP) and proinflammatory cytokines like interleukin-2 (IL-2), interleukin-6 (IL-6), interleukin-10 (IL-10), gamma interferon (INF), and tumor necrosis factor-alpha (α-TNF) are higher in severe COVID-19." (PMID 38013720, 2022).
COVID-19 (continued). "However, values for IL-2 failed to associate with COVID-19 mortality (not shown), and this could probably be because the IL-2 concentration was very low, close to the detection threshold." (PMID 35663992, 2022). "The antigen-specific T cell response in actively infected COVID-19 patients was predominated by a Th1 phenotype with a significant increase in cytokines, such as IFN-γ, TNF-α, and IL-2 by V3." (PMID 36298628, 2022). "In female patients with COVID-19, 25(OH)D was inversely correlated with CRP (R = −0.51, p < 0.05), and borderline significant inverse correlations with IL-2 (R = −0.5, p = 0.06) and IL-17α (R = −0.36, p = 0.06) were observed." (PMID 36554094, 2022). "The concentrations of granulocyte colony-stimulating factor (G-CSF), IL-2, IL-7, IL-10, TNF, and the chemokines, CCL2, CCL3, and CXCL10 were extremely high in the plasma of patients with severe COVID-19." (PMID 36294868, 2022). "NLRP3 inflammasome activation primed and stimulated host inflammatory response, and the inflammatory cytokines (including IL-1β, IL-2, IL-6, IL-8, IL-18, and TNF-α) have been identified to be related to disease severity in COVID-19 patients." (PMID 34979342, 2022). "Based on these effects of NFV on CYPA activity and IL-2 production, further research of NFV's effect in human COVID-19 patients is warranted." (PMID 34677780, 2022). "Clinical investigations have revealed that the vaccines trigger human antibody and Th1 cell response, which increases blood levels of IL-2, TNF-α and interferon (IFN)-gamma as a response to COVID-19 viral antigen." (PMID 35755518, 2022). "Participants that responded to polyclonal stimuli by increasing IL-2 and IFN-gamma production and decreasing PD-1 expression in CD4+ and CD8+ T cells tended to develop mild COVID-19 symptoms." (PMID 35860236, 2022). "Our results reported that mothers affected by COVID-19 have an increase in pro-inflammatory factors (TNF-α, IL-2, TGF-β, IL-6 and IL-8) and at the same time, in anti-inflammatory agents such as IL-10, when compared to controls." (PMID 35408809, 2022). "Representative dot-plots exemplify the contrast of CD3+CD4+ T cells simultaneously expressing IL-2, IFN-gamma, and PD-1 in whole blood samples exposed to polyclonal molecules from participants who experienced mild or severe COVID-19 throughout the follow-up." (PMID 35860236, 2022). "High pro-inflammatory cytokines and chemokines, such as IL-1β, IL-2, IL-6, IL-7, IL-10, TNF-α, IFN-γ, G-CSF, CCL2, CXCL10 were detected on COVID-19 patients." (PMID 35305698, 2022). "This information illustrates why trying to clarify the contribution of immune cells and mediators such as CD4+ T cells, CD8+ T cells, IL-2, IFN-gamma, and PD-1 to COVID-19 progression is extremely hard in polytreated patients already hospitalized." (PMID 35860236, 2022). "TNF, GAPDH, MAPK3, MAPK1, EGFR, CASP3, MAPK8, mTOR, IL-2, and MAPK14 are important targets for YQS in COVID-19 treatment." (PMID 35340244, 2022). "In the COVID-19 pathway, the SARS-CoV-2 receptors ACE2 and NRP1, some immune molecules such as IL-2, STAT1, and some complement molecules are the targets of tuftsin." (PMID 35402510, 2022). "It has been suggested that decreased levels of IL-2, IL-2R, JAK1, and STAT5 are the reason why lymphopenia occurs with severe COVID-19." (PMID 35562935, 2022). "A decrease in natural killer T and B cells and increased expression of IL-2, IL6, IL10, TNF-α, and interferon-γ (INF-γ) were observed in the COVID-19 pathophysiology." (PMID 35656183, 2022). "Acute inflammation increases cytokine load, such as IL-2, IL-7, and TNF, which contribute to the cytokine storm seen in COVID-19." (PMID 35746659, 2022). "From a different perspective, our strategy involving unspecific polyclonal stimuli prior to infection allows us to expand on the body of evidence supporting that PD-1 expression increases as IL-2 and IFN-gamma production decreases in severe COVID-19." (PMID 35860236, 2022).
COVID-19 (continued). "TCD4/SARS-CoV-2 show lower polyfunctional capacity (INF-γ, IL-2 and TNF-α) in aTB/COVID-19 vs. COVID-19." (PMID 36090983, 2022). "It remains to be defined why COVID-19 patients had severe and critical clinical characteristics independent of circulating levels of inflammatory cytokines (IFN-γ, TNF-α, IL-2, IL-4 and IL-10)." (PMID 34123873, 2021). "In our analysis, we identified two target gene clusters of biochanin A including inflammatory genes (IL1A, IL2, and IL6R) and cell proliferation genes (CCND1, PPARG, and EGFR) relevant to the treatment of CRC/COVID-19." (PMID 34931923, 2021). "Our results showed that critically ill COVID-19 patients had increased serum levels of IL-1β, IL-1RA, IL-6, IL-9, and CXCL10, and lower levels of IL-2 and IL17A as compared to healthy volunteer donors." (PMID 33995342, 2021). "An increased expression of IL-2 (p < 0.001) and INF-gamma (p = 0.024) and a reduction of IL-12p70 (p < 0.001) in COVID-19 patients were observed regarding the Th1 cytokines." (PMID 33718270, 2021). "As for wave 1, significant differences and increasing trends of IL-1β, IL-1ra, IL-2, IL-6, IL-8, IL-10, GM-CSF, IFN-γ, IP-10, were observed in the three groups (Controls ≤ Mild COVID-19 ≤ Severe COVID-19)." (PMID 34675240, 2021). "Our results showed that Spike IFN-γ, Spike IP-10, Spike IL-2; NP Pool1 RANTES; NP Pool2 IP-10 and ORF3a IL-2 are the most important in vitro conditions to distinguish COVID-19- from NO-COVID-19-subjects over all the antigen stimulations." (PMID 34174875, 2021). "Studies have shown that the levels of various cytokines such as IL-2R, IL-6, IL-10, IL-2, IL-7, GCSF and TNF-α are significantly higher in patients with severe COVID-19 compared with patients who have a mild disease." (PMID 34490065, 2021). "Pathway analysis between Ephedra-Glycyrrhiza and COVID-19 showed that the key targets were TNF-α, IL2, FOS, ALB, and PTGS2." (PMID 33581688, 2021). "The majority of COVID-19 patients had normal levels of TNF-α (40/52, 76.9%), IL-2 (47/52, 90.4%) and IL-4 (36/52, 69.2%)." (PMID 34123873, 2021). "We identified a COVID-19 signature based on six immune factors: IFN-γ, IP-10 and IL-2 induced by Spike; RANTES and IP-10 induced by NP and IL-2 induced by ORF3a." (PMID 34174875, 2021). "High levels of inflammatory cytokines in COVID-19 patients, such as IFN-γ and IL-2, can stimulate lipid peroxidation of human spermatozoa and increase DNA fragmentation of spermatozoa, thus impairing sperm motility and viability." (PMID 34122351, 2021). "The severity of COVID-19 is attributed to the inflammatory status, presented as an increased inflammatory biomarker such as C-Reactive Protein (CRP), Interleukin 2 (IL-2), and Interleukin 6 (IL-6), which are predictors of mortality." (PMID 34903765, 2021). "SARS-CoV-2 antigen peptide pools-stimulated-IL-2 and -IFN-γ response can distinguish COVID-19 convalescent individuals from healthy donors." (PMID 34234102, 2021). "IL-2 was lower in COVID-19 patients than in healthy individuals, while IL-4, IL-6, CCL2, IFN-γ, and TNF-α were higher in COVID-19 patients than in healthy individuals." (PMID 34489974, 2021). "Our present results identified obvious elevations of various cytokines in patients with severe COVID-19, including IL-1α, IL-1β, IFN-γ, TNF-α, IL-2, IL-4, IL-6, IL-10, and IL-17A." (PMID 34113636, 2021). "Conversely, in non–COVID-19 controls, most SARS-CoV-2–reactive CD4+ T cells were distributed between triple functional cells (IL-2+IFN-γ+TNF-α+) and cells coproducing IFN-γ and TNF-α." (PMID 33945513, 2021). "As expected, the magnitude of IFNγ, IL-2 and TNF producing effector cells was significantly elevated in COVID-19 patients." (PMID 34228322, 2021). "In COVID-19, the CD4 response was characterized by limited expression of IFN-γ and was enriched in cells coexpressing IL-2 and TNF-α." (PMID 33945513, 2021).
COVID-19 (continued). "In our study, we found that the core pathogenesis target of COVID-19 was TNF, while the secondary pathogenesis targets included IL6, IL10, and IL2 cytokines." (PMID 34731090, 2021). "Spike protein from SARS-CoV-2 showed to be a good T-cell stimulation for COVID-19, with high production of IFN-γ, IL-2, and TNF by CD4+ T cells, characterizing the predominant response of Th1 cells." (PMID 34571855, 2021). "For example, the increase in IL-2, MMP9, and VEGFA is related to the mortality of COVID-19 patients." (PMID 34803696, 2021). "In the COVID-19, Th1 cells were significantly higher than Th2 CD4+ T cells, which produced IL-4, IL-2, and TNF, main markers for Th2 response." (PMID 34571855, 2021). "The increase in blood concentrations of different cytokines such as interleukins and chemokines such as IL-6, IL-8, IL-10, TNF-α, IL-1β, IL-2, IP-10, MCP-1, CCL3, CCL4, and CCL5 has been described for COVID-19 patients." (PMID 34262570, 2021). "The predictive value of the antigen peptide pools stimulated-IL-2 and -IFN-γ for COVID-19 convalescent individuals was also confirmed." (PMID 34234102, 2021). "Regarding the general cell response, we present the following findings: autopsies of patients with COVID-19 revealed increased cell exhaustion and SARS-CoV-2 CD4+ expressing IFN-γ, TNF-alpha, and IL-2 indicating a Th1 cellular response." (PMID 34571855, 2021). "Previous studies have reported abnormal levels of IL-2, IL-6, IL-7, IL-10, CRP, and tumor necrosis factor-α in COVID-19 patients." (PMID 34242179, 2021). "Increased cytokine secretion, including IL-2, IL-4, IL-6, IL-10, tumor necrosis factor (TNF)-α, and IFN-γ, in COVID-19 patients has been reported." (PMID 33445583, 2021). "In patients who ultimately died of COVID-19, many chemokines responsible for monocyte and T cell recruitment and survival such as CCL1, CCL2, M-CSF, IL-2, Il-16, and CCL21 were elevated, suggesting pathological roles associated with host defense factors." (PMID 34198973, 2021). "We have identified gene clusters associated with CRC, COVID-19, and biochanin A. Bioinformatic analysis further showed the involvement of six core targets of biochanin A in the treatment of CRC/COVID-19, including EGFR, CCND1, IL2, IL1A, IL6R, and PPARG." (PMID 34931923, 2021). "High plasma levels of pro-inflammatory cytokines (interleukin-2, interleukin-7, granulocyte colony-stimulating factor, IP10, MCP1, MIP1A and tumor necrosis factor-α) have been observed in critically ill COVID-19 patients admitted to intensive care units." (PMID 33752721, 2021). "We also noted that, in the COVID-19-naive population, the frequency of AIM+IL-2+CD8+ T cells was greater among the older than among the younger, but frequencies of IFNγ+, TNFα+, or triple+ CD8+ T cells were not different." (PMID 34868051, 2021). "Increased IL-2, IL-6, TNF-α, and IFN-γ were detected in trophoblast cells and maternal blood of COVID-19 placentas." (PMID 35071136, 2021). "Other researchers also reported elevated levels of IL-2, IL-4, and INF-γ in patients with COVID-19 31, 32, and that these levels were highly correlated with disease progression." (PMID 33967617, 2021). "Using the network pharmacology approach, we identified two clusters of genes involved in immune response (IL1A, IL2, and IL6R) and cell proliferation (CCND1, PPARG, and EGFR) mediated by biochanin A in CRC/COVID-19 condition." (PMID 34931923, 2021). "Aiming at finding discriminant oral cytokines for COVID-19 status, we employed volcano plot and VIP plot, finding out seven COVID-19-related discriminant cytokines (IL-6, IL-5, GCSF, IL-2, TNF-α, GMCSF, and INF-γ), while only one (IL-12p70) for controls." (PMID 34394024, 2021). "Combined analyses of all measured cytokines (IL-2, IFN-γ, and TNF-α) showed that the overall polyfunctional profile of SARS-CoV-2–specific cells in COVID-19 participants was distinct from uninfected controls (P < 0.0001)." (PMID 33945513, 2021).
COVID-19 (continued). "Spike-stimulated PBMCs exhibited high CD8+ T-cell frequencies, with IFN-γ, IL-2, and TNF production in COVID-19." (PMID 34571855, 2021). "In contrast, the highest contributors to dimension 1 were IL-21, IL-2, IL-1b, IL-17A, GM-CSF, IFN-γ, IL-7 and CCL3, and these cytokines were significantly decreased in acute COVID-19 patients in comparison to HC." (PMID 34572439, 2021). "In patients with severe COVID-19, we found that TNF-α was satisfactorily correlated with IL-2, IL-4, and IFN-γ, and monocytes were negatively correlated with IL-2, IL-4, and TNF-α." (PMID 34712741, 2021). "It was first reported that several pro-inflammatory cytokines and chemokines, including IL-2, IL-7, IL-10, CXCL10 (IP-10), CXCL8, CCL2 (MCP1), TNFα, and IFNγ were higher in the plasma of COVID-19 patients as compared to healthy controls." (PMID 33363221, 2020). "In COVID-19, a significant elevation of cytokines (interferon [IFN]-γ, tumor necrosis factor [TNF]-α, interleukin [IL]-6, IL-10, IL-2, IL-1, and others) and lymphocytopenia are found." (PMID 32510901, 2020). "Patients with severe or fatal COVID-19 showed significantly higher levels of inflammatory factors, such as CRP, interleukin-6 (IL-6), interleukin-2 (IL-2) and interleukin-7 (IL-7)." (PMID 32719804, 2020). "COVID-19 patients had lower levels of most classical inflammatory cytokines (G-CSF, CCL20, IL-1β, IL-2, IL-6, IL-8, IL-15, TNF-α, TGF-β), but higher plasma concentrations of CXCL10, GM-CSF and CCL5, compared to non-COVID-19 patients." (PMID 33272291, 2020). "Some of these proinflammatory cytokines, including IL-2, IL-7, IL-10, G-CSF, IP-10, MCP-1, MIP-1a, and TNF-α, are highly elevated in the blood of severely ill COVID-19 patients." (PMID 33101440, 2020). "The stimulation of PBMCs from COVID-19 patients with S protein peptides resulted in production of effector or Th1 cytokines (IFN-γ, TNF-α, and IL-2) and, to a lesser extent, Th2 (IL-5, IL-13, IL-9, and IL-10) and Th17 (IL-17A, IL-17F, and IL-22) cytokines." (PMID 32916812, 2020). "NK cells showed lower percentages of CD107a, IFN-γ, IL-2, TNF-α and granzyme B than those in healthy donors in COVID-19 patients." (PMID 33371901, 2020). "As summarized in, in comparison with six controls, a significantly higher amount of CD4+ T cells from eight COVID-19 patients was able to produce TNF, CD107a, IFN-γ, IL-2, and particularly IL-17 (that showed the highest difference)." (PMID 32632085, 2020). "Virus-specific T cells from severe COVID-19 patients also highlight a central memory phenotype with high levels of interferon (IFN)-γ, tumor necrosis factor (TNF)-α, and IL-2." (PMID 33344479, 2020). "Results showed that COVID-19 patients have higher serum level of cytokines (TNF-α, IFN-γ, IL-2, IL-4, IL-6 and IL-10) and CRP than control individuals." (PMID 32475230, 2020). "A previous study demonstrated the changes in the levels of inflammatory cytokines, such as IL-2, IL-7, IL-10, and tumor necrosis factor (TNF)-α, in the serum of COVID-19 patients." (PMID 32484453, 2020). "There are higher levels of inflammatory factors, including IL-2, IL-4, IL-6, IL-10, TNF-α, and IFN-γ, found in COVID-19 patients than in healthy people." (PMID 32985562, 2020). "Consistently, increased levels of T-cell-related cytokines (IL-2, MIP-1α, MIP-3α, IL-10, Eotaxin, IL-8, IL-17A–D, and IL-22) have been found in plasma of individuals with DS; among them IL-10 and IL-8 are upregulated in severe COVID-19." (PMID 41490093, 2026). "This study specifically examined the spike-specific immune response following a third dose of mRNA COVID-19 vaccines by assessing Th1 cytokines (IFN-γ, IL-2, and TNF-α) and IP-10 production using an easy-to-use whole-blood assay in PwMS undergoing various DMTs." (PMID 41246331, 2025). "Moreover, patients with severe COVID-19 and poor prognosis have lower levels of IL1B, IL2, and IL8 compared to those with favorable outcomes." (PMID 41155463, 2025).